POLE (DNA polymerase epsilon, catalytic subunit)
Diseases named in the same sentence as POLE in open-access papers (continued):
Sharing a sentence is not in itself a finding about the gene and the disease.
medulloblastoma (6 papers, 2020 to 2025). A malignant, invasive embryonal neoplasm arising from the cerebellum. "The hypermutated tumor profile seen in our patient may have been driven by the POLE mutation, which encodes a proofreading polymerase known to drive hypermutation in medulloblastoma." (PMID 40958970, 2025). "Our patient had additional mutations at POLE, LYST, KMT2D, and TERT, all of which have been shown to significantly reduce overall survival in medulloblastoma." (PMID 40958970, 2025). "Of the four known molecular subgroups in medulloblastoma–SHH, WNT, Group 3, and Group 4—both the POLE‐mutated cases belonged to the SHH subgroup." (PMID 34351088, 2022). "The second published case describes a patient born into a known PPAP family carrying the familial POLE PV c.830A>G (p.E277G), who presented with a Sonic Hedgehog-activated medulloblastoma at 4.5 years of age." (PMID 36291559, 2022). "However, in this study we identify five tumors with >10 Mut/Mb and two of them with POLE mutations belonging to the SHH subgroup, suggesting high TMB does occur, albeit rarely, in medulloblastoma." (PMID 34351088, 2022).
serous carcinoma (6 papers, 2017 to 2023). "In one patient with mixed uterine CCC/serous carcinoma, a POLE hotspot mutation (c.857C>G) was found (both components could not be separately extracted)." (PMID 37081760, 2023). "In the POLE-mutated group, the non-endometrioid histologic types were four mixed carcinomas, one serous carcinoma, and two clear-cell carcinomas." (PMID 30917185, 2019).
Familial adenomatous polyposis (5 papers, 2016 to 2025). Familial adenomatous polyposis (FAP) is characterized by the development of hundreds to thousands of adenomas in the rectum and colon during the second decade of life. "The main autosomal dominant adenomatous polyposis syndromes include familial adenomatous polyposis (FAP) and polymerase proofreading-associated polyposis (PPAP), caused by germline PVs in APC and the POLE and POLD1 genes, respectively." (PMID 40237887, 2025). "First, we searched for deleterious variants in the genes associated with adenomatous polyposis of the colon (APC, MUTYH, NTHL1, POLD1, and POLE)." (PMID 27217144, 2016). "People with polyposis could have a genetic basis with germline mutations in polyposis-related genes, such as the APC gene, resulting in familial adenomatous polyposis (FAP), MUTYH-associated polyposis (MAP), or, rarely, in other genes such as AXIN2, GREM1, NTHL1, POLE, POLD1, or MSH3." (PMID 40095498, 2025).
hereditary colorectal cancer (5 papers, 2014 to 2025). "Finally, related to hereditary colorectal cancer, 11 variants in POLE and 6 variants in POLD1 were found." (PMID 36232851, 2022).
prostate carcinoma (5 papers, 2021 to 2025). A carcinoma that arises from epithelial cells of the prostate gland. "Targeted genome sequencing of highly purified light-chain specific CLL clones from this patient and from the prostate carcinoma revealed the presence of a rare germline polymorphism in the POLE gene." (PMID 34502317, 2021). "In a study involving a cohort of 4129 prostate cancer patients 1.8% (74/4129) of patients had POLE/POLD1 mutations." (PMID 34063238, 2021). "Despite some recent reports that POLE and POLD1 variants predispose to prostate cancer, only one patient developed prostate cancer (aged 51) in the families analysed." (PMID 33948826, 2022). "Based on this rationale, a phase 2 study of toripalimab (a PD-1 antibody) in patients with advanced solid organ tumors including prostate cancer and POLE/POLD1 positive status has been initiated." (PMID 34063238, 2021). "The prostate cancer case also had P/LPGVs in BARD1, NF2, and POLE, all of which were not reported on the TGP." (PMID 41465149, 2025).
colon adenocarcinoma (4 papers, 2020 to 2026). "We present a rare case of a 41-year-old Chinese female with a right-sided colon adenocarcinoma who harboured a (p.P286R) POLE somatic mutation." (PMID 32758138, 2020). "TCGA PanCancer Atlas dataset comprised 378 samples of colon adenocarcinoma, including 44 MSI (11.6%), 206 CIN (54.5%), 36 GS (9.5%), and 5 POLE mutations (1.3%)." (PMID 34026821, 2021).
endometrioid endometrial carcinomas (4 papers, 2021 to 2025). "The ultramutated subgroup mostly consists of high-grade endometrioid endometrial carcinomas, presenting a very high mutational frequency, with mutations in the Polymerase-ε (POLE) exonuclease domain, and a good prognosis." (PMID 33917330, 2021).
ovarian endometrioid carcinoma (4 papers, 2017 to 2025).
ovarian tumor (4 papers, 2018 to 2024). "Signature 10 was identified in the CRC (contribution: 23%), and signature 14, linked to the co-occurrence of MMR deficiency and POLE ED pathogenic variant in the ovarian tumor (contribution: 15.32%)." (PMID 32792570, 2020). "Endometriosis-related ovarian neoplasms (ERONs) have recently attracted considerable attention; however, the prevalence and patterns of ARID1A and POLE mutations in ERONs have not been studied in detail." (PMID 29599905, 2018).
squamous cell carcinoma (4 papers, 2018 to 2020). A carcinoma arising from squamous epithelial cells. "Of patient cohorts, 6% and 5.6% were positive for a POLE mutation in adenocarcinoma and squamous cell carcinoma, respectively." (PMID 32365882, 2020). "Results indicated POLE mutations as a favorable biomarker for improved OS in squamous cell carcinoma patients (p = 0.033) only, although POLE mutated adenocarcinomas with high expression of PD-L1 also exhibited improved OS (p = 0.024)." (PMID 32365882, 2020). "In the KUMC cohort, POLE mutants were evaluated in 168 primary cancers (137 cases of adenocarcinoma and 31 cases of squamous cell carcinoma)." (PMID 32433714, 2020). "Utilizing the data of 513 patients with adenocarcinoma (LUAD) and 497 patients with squamous cell carcinoma (LUSC) from The Cancer Genome Atlas (TCGA) cohort, we tested the prognostic value of POLE mutations and programmed cell death ligand 1 (PD-L1) expression in the two main subtypes of NSCLC." (PMID 29650000, 2018).
uterine tumors (4 papers, 2018 to 2025). "We classified uterine tumors into four molecular subtypes based on the TCGA method: POLE ultra-mutated, MSI, low CN, and high CN." (PMID 39518118, 2024). "The favorable prognosis included patients with high tumor stage, which echoes prior studies demonstrating a favorable outcome of uterine tumors with POLE exonuclease mutations despite adverse standard clinicopathologic indicators including high grade, high stage, and lymphovascular invasion." (PMID 32838755, 2020). "This subtype harbours POLE mutations and is predominantly found in colorectal and uterine tumours." (PMID 29880869, 2018).
bladder cancer (3 papers, 2022 to 2025). "While UTUC is generally considered less immunogenic than bladder cancer, cases with high TMB or POLE mutations may benefit from ICIs." (PMID 41395625, 2025).
breast tumor (3 papers, 2020 to 2023). "Strikingly, among these tumors, one breast tumor showed both an ultra-mutational signature and MMR deficiency resulting from the germline POLE T278K mutation and the secondary somatic MMR mutations." (PMID 36765365, 2023). "Two primary breast tumors from two carriers of POLE p.Glu396Thrfs*15 were analyzed by exome sequencing." (PMID 32792570, 2020). "Sequencing data from a breast tumor harboring a somatic frameshift variant in the same residue as the germline POLD1 c.3305delC (p.Pro1102Leufs*22) showed neither hypermutation nor the POLE/D1-associated mutational signature." (PMID 32792570, 2020).
clear cell carcinomas (3 papers, 2019 to 2022). "Endometrioid and clear cell carcinomas, frequently associated with endometriosis, are characterized by alterations of CTNNB1, PTEN, and POLE mutations, while clear cell carcinomas are characterized by ARID1A mutations." (PMID 35163166, 2022).
Fanconi anemia (3 papers, 2018 to 2025). Fanconi anemia (FA) is a hereditary DNA repair disorder characterized by progressive pancytopenia with bone marrow failure, variable congenital malformations and predisposition to develop hematological or solid tumors. "Most detected variants affected the Fanconi anemia/DNA repair pathway (34%, ATM, FANCA, FANCI, MLH1, MSH6, POLE, RAD51C, RAD51D) followed by mutations altering the SWI/SNF (SWItch/sucrose non-fermentable) complex (22%, ARID1A and SMARCA4)." (PMID 34200508, 2021). "Among these are polymerase (DNA directed), epsilon, catalytic subunit (POLE); PTEN; Fanconi anemia, complementation group A (FANCA); and CCR4-NOT transcription complex, subunit 3 (CNOT3) and others." (PMID 30143704, 2018).
hepatocellular carcinoma (3 papers, 2022 to 2023). A malignant tumor that arises from hepatocytes. "We present a patient with hepatocellular carcinoma with a rare POLE mutation (V1368M) outside the exonuclease-domain predicted to be deleterious, a low TMB (1 mut/Mb), and microsatellite stability, who demonstrated an exceptional response to pembrolizumab." (PMID 35274726, 2022). "This article presents the case of a patient with hepatocellular carcinoma with a rare POLE mutation outside the exonuclease domain, who demonstrated an exceptional response to pembrolizumab." (PMID 35274726, 2022). "To challenge this paradigm, we present a patient with hepatocellular carcinoma (HCC) with a rare deleterious POLE mutation outside the exo-domain with a low TMB of 1 mut/Mb and microsatellite stability (MSS) who demonstrated an exceptional response to pembrolizumab." (PMID 35274726, 2022). "As a marker for early detection of hepatocellular carcinoma, POLE may also promote the activity of these immune cells and strengthen the phagocytosis of cancer cells." (PMID 35812186, 2022). "It is suggested that more in-depth research needs to be explored, and the prognosis of hepatocellular carcinoma or the expression of POLE may be affected by hormone levels or ethnic differences." (PMID 35812186, 2022). "Backgrounds: Liver hepatocellular carcinoma (HCC) is one of the most common cancers worldwide, and POLE, playing an important role in maintaining genetic stability, is closely connected with cancer prognosis." (PMID 35812186, 2022). "With the samples of liver hepatocellular carcinoma (HCC) in TCGA database (n=421) and ICGC database (n=442), we compared the expression level of POLE in normal tissues and tumor tissues, and found that POLE expression was significantly higher in tumor tissues." (PMID 35812186, 2022).
hereditary mixed polyposis syndrome (3 papers, 2016 to 2022). "Recently, genome-wide screening efforts led to the identification of mutations affecting the expression of GREM1 as the cause of hereditary mixed polyposis syndrome (HMPS) and mutations in the POLD1 and POLE genes as the cause of polymerase proofreading-associated polyposis (PPAP) syndrome." (PMID 27279102, 2016).
IMAGEI syndrome (3 papers, 2023 to 2025). "Similarly, impaired S phase progression was detected in fibroblasts from patients with biallelic POLE variants and IMAGEI syndrome." (PMID 37990341, 2023). "Biallelic pathogenic genetic variants in POLE lead to the development of autosomal recessive diseases: FILS syndrome (OMIM #615139) and IMAGE-I syndrome (OMIM #618336)." (PMID 38201513, 2023).
lymphoma (3 papers, 2013 to 2023). A malignant (clonal) proliferation of B- lymphocytes or T- lymphocytes which involves the lymph nodes, bone marrow and/or extranodal sites. "We found that mutation rates of contexts subject to localized mutational processes (UV-signature 7a, POLE-signature 62, lymphoma-signature 72, and unknown etiology-signature 17b) were 4–9-fold increased compared to what can be explained by cancer type and mutational signature alone." (PMID 37592287, 2023). "We also found hotspot-enriched signatures related to UV (signatures 7a, 67, 75, 7b), POLE (62, 10a), POLI, lymphoma-linked, and several signatures of unknown etiologies (17b, 17a, 19, 68, 28, 30)." (PMID 37592287, 2023). "These include AKT3, ERCC5 and maybe ARID1A as general MMR-D targets, but also POLE as lymphoma-specific neoantigen." (PMID 31581674, 2019). "The difference in the expression patterns of genes between the healthy and DLBCL samples in the canine dataset highlighted important lymphoma-specific up-regulated genes including DHFR, MS4A1, MYC, POLA1, POLE, RRM1, TOP2A and TYMS." (PMID 24023754, 2013).
meningioma (3 papers, 2019 to 2023). A generally slow growing tumor attached to the dura mater. "The present study builds on the characterization of POLE as a potentially protective mutation in meningiomas." (PMID 36514795, 2022). "It remains to be seen if POLE mutant meningiomas would garner the same beneficial outcomes from checkpoint inhibitors." (PMID 36514795, 2022). "Within a large panel of clinically actionable driver mutations, matched primary and recurrent meningiomas exhibited similar genomic alterations, most commonly in NF2 and POLE genes." (PMID 31191822, 2019). "POLE variants, which were also present in 12 tumors (32%) in the sample and encode for the catalytic subunit of DNA polymerase epsilon, have not commonly been identified in prior meningioma genomic studies, but have been implicated in syndromes related to neurofibromatosis type 1." (PMID 31191822, 2019).
metastatic tumors (3 papers, 2017 to 2022). "However, (although infrequently occurring) POLE-mutant and MSI patients with recurring or metastatic disease are possible candidates." (PMID 28344870, 2017).
cervical cancer (2 papers, 2015 to 2023). A primary or metastatic malignant neoplasm involving the cervix. "Endometrial and cervical cancer profiles correlated mainly with the expression profile of POLE and MSI subcategories, while vulvar carcinoma was found to deviate from those profiles." (PMID 26559525, 2015).
duodenal cancer (2 papers, 2022 to 2025). "Ten of 105 (9.5%) probably pathogenic POLE ED variant heterozygotes developed duodenal cancer (DC; median age 55) and 16 (15%) developed one or more duodenal adenomas (DAs; median age 43)." (PMID 33948826, 2022). "Until now, duodenal cancers had been described exclusively in POLE heterozygotes, a discrepancy that may partly reflect the smaller number of reported POLD1 families compared with POLE." (PMID 41487566, 2025).
endometrioid ovarian cancers (2 papers, 2017 to 2021). "Somatic POLE mutations are uncommon in serous ovarian cancer (OC) but the presence of POLE mutations is increasingly recognized in ovarian endometrioid cancer (OEC)." (PMID 34158040, 2021). "In the TGS set we observed recurrent POLE mutations in 14% (2/14) of endometrioid ovarian cancers." (PMID 28852190, 2017).
Ewing sarcoma (2 papers, 2020 to 2025). A small round cell tumor that lacks morphologic, immunohistochemical, and electron microscopic evidence of neuroectodermal differentiation. "While POLE suppression had a relatively modest effect on rhabdomyosarcoma viability, we noted a more dramatic effect in A673 (Ewing sarcoma cells with known high replicative stress) that was not shared with other Ewing sarcoma cells (CHLA10)." (PMID 40760094, 2025). "In order to assess the relative selectivity of POLE inhibition in CIC::DUX4 sarcomas, we tested the impact of POLE expression on non-CIC::DXU4 sarcoma subtypes, including rhabdomyosarcoma cells (Rh30, RD) and Ewing sarcoma (CHLA10, A673)." (PMID 40760094, 2025). "Interestingly, POLE expression was decreased in A673 and TC32 cells following THZ531 treatment, suggesting that POLE may, in part, contribute to the survival of Ewing sarcoma cells under high replication stress conditions imposed by EWS/FLI-mediated transcription." (PMID 40760094, 2025).
gastric adenocarcinoma (2 papers, 2021 to 2022). "Recent studies have shown that gastric adenocarcinoma with POLE mutations or microsatellite instability–high (MSI-H) had DNA MMR signatures and higher TMBs." (PMID 34540650, 2021).
mucinous adenocarcinoma (2 papers, 2017). An invasive adenocarcinoma composed of malignant glandular cells which contain intracytoplasmic mucin. "Case T368, with the POLE mutations c.901G>A, p.Asp301Asn, and c.1376C>T, p.Ser459Phe, was a man who was diagnosed at age 49 years with a mucinous adenocarcinoma located in the cecum and invading the muscle layer." (PMID 29072370, 2017). "It is noteworthy that we found two mucinous adenocarcinomas of colon associated with POLE variants." (PMID 29212164, 2017).
Obesity (2 papers, 2016 to 2020). Accumulation of substantial excess body fat. "An expanding signs of EC molecular diversity [see f.e. data on POLE gene mutations analysis] is also ‘an item’ to be considered during analysis of obesity connection with risk factors, as well as with clinical and morphologic features of EC." (PMID 27853670, 2016).
pilomatricoma (2 papers, 2020 to 2023).
protein deficiency (2 papers, 2021 to 2024). "GB patients with MMR protein deficiency or POLE mutations have been reported to have a high treatment response rate." (PMID 33741903, 2021).
renal carcinoma (2 papers, 2019 to 2020). A carcinoma arising from the epithelium of the renal parenchyma or the renal pelvis. "POLE c.1277C>T (p.Ala426Val) (MAFgnomAD_NFE = 0.0034%), affecting a highly conserved residue within the Exo IV motif active site, was identified in a male diagnosed with CRC and multiple adenomas at age 44 and with renal cancer at 49, and in his CRC-affected paternal uncle." (PMID 32792570, 2020).